IL10 (interleukin 10)
Diseases named in the same sentence as IL10 in open-access papers (continued):
Sharing a sentence is not in itself a finding about the gene and the disease.
tumor (continued). "Finally, in T-cell lymphocyte proliferation, monocyte-derived cells fail to mature into DCs and protect tumor cells by preventing their death due to tumor IL-10 secretion." (PMID 39464313, 2024). "Cancer cells hinder the proliferation of cytotoxic T lymphocytes (CTLs) within the tumor through the production of immunosuppressive cytokines like interleukin (IL)-10, vascular endothelial growth factor (VEGF), and TGF-β, and by consuming IL-2, a critical cytokine for CTL function." (PMID 38730572, 2024). "Our findings suggest a prognostic role for interleukin-10 that may be related to its immunosuppressive function in the tumor microenvironment." (PMID 39199610, 2024). "As an immunosuppressive molecule that enables tumors to evade immune surveillance, IL-10 might act as a potential promoter of tumor growth, leading to more aggressive behavior of malignant cells." (PMID 38339076, 2024). "Furthermore, we analyzed the correlation between LINC00665 levels in metastatic lung cancer patients and immune-suppressive cytokines (TGF-β, IL-10, and IL-1β) as well as anti-tumor cytokines (IFN-γ, IL-2, and TNF-α)." (PMID 38951802, 2024). "Interestingly, SAADKO tumor-bearing mice also had reduced levels of IL-10, a cytokine with complex roles in both promoting and resolving inflammation." (PMID 39336082, 2024). "While IL-10 alone could be responsible for both M2 and lymphatic phenotypes of tumor M-LECP, it raised the question of specificity of its effect as this pathway is also involved in determining the fate of many other lineages." (PMID 38640116, 2024). "Interestingly, even before treatment, the number of cells producing interleukin-10, an anti-inflammatory cytokine, was an indicator of tumor burden at the end of treatment." (PMID 38473247, 2024). "Evidence suggests that this dysfunction may partially arise from a suppressive tumor microenvironment characterized by elevated cytokines (like IL-10 and TGF-β) that inhibit DC maturation." (PMID 38730679, 2024). "Specifically, IL-10 promotes angiogenesis in the tumor and inhibits cytotoxic T cell activation." (PMID 39085255, 2024). "TNF-α and IL-10, which are secreted by M2-like macrophages, can induce PD-L1 expression in an autocrine manner, and inhibiting T cell function, which has a strong promoting effect on the occurrence and development of tumours." (PMID 38475858, 2024). "IL-10 protein trap treatment reduced immunosuppressive cell function including MDSCs, leading to activation of anti-tumour cells such as NK cells thereby suppressing tumour growth." (PMID 38464388, 2024). "Interestingly, the inflammatory angiostatic cytokines MIG, M-CSF, IL-10, and IFNγ were found to decrease in time-to-tumor progression." (PMID 39451257, 2024). "Another report suggests that C5a may directly affect CD8+ T cell function by inhibiting interleukin-10 (IL-10)-dependent T cell-mediated antitumor immunity to promote tumor growth." (PMID 38098230, 2024). "Notably, PD-L1 in tumor cells promotes immune suppression by increasing IL-10 production in peripheral regulatory T cells." (PMID 39628695, 2024). "Since ferritin and cytokines (including IL10) are known to be produced by some tumour cells, the high ferritin and M2 macrophage numbers here could also reflect paracrine manipulation of the immune response by the tumour cells owing to the tumour biology." (PMID 39259401, 2024). "Moreover, puerarin decreases the level of pro-tumor cytokines (IL-10, TGF-β, and IL-4) and increases the expression of anti-tumor cytokines (IFN-γ, IL-12, and TNF-α)." (PMID 38361933, 2024). "This statement is supported by an increase in anti-inflammatory cytokines IL-4 and IL-10, both as an evasion of the immune response to tumor cell growth and due to relatively high levels of estrogen and progesterone, which also activate anti-inflammatory cytokines." (PMID 39456554, 2024).
tumor (continued). "The observed reduction in IL10RB levels associated with increased physical activity suggests that physical activity may modulate IL-10 signaling pathways, potentially enhancing anti-tumor immune responses." (PMID 39769247, 2024). "Conversely, IL-10, with its anti-inflammatory properties, may create a microenvironment conducive to MM progression by dampening immune surveillance and promoting tumor cell survival." (PMID 39413115, 2024). "This enhancement is further characterized by increased production of interferon-gamma (IFN-γ) and interleukin-2 (IL-2) within the TME, concurrent with downregulation of tumor necrosis factor-alpha (TNF-α) and interleukin-10 (IL-10), thereby fortifying the host’s anti-tumor defenses." (PMID 38930435, 2024). "High IL-10 levels are secreted by immature DCs accumulating around tumor foci." (PMID 38279997, 2024). "This polarization was further confirmed by the increased level of interleukin‐12 (IL‐12, the predominant cytokine secreted by M1‐like TAMs) and the reduced level of interleukin‐10 (IL‐10, the predominant cytokine secreted by M2‐like TAMs) in the tumor microenvironment (TME) of the three groups." (PMID 39467056, 2024). "For instance, cytokines typically classified as immune response-inhibitory cannot be categorically labeled as pro-tumoral cytokines, as exemplified by the case of IL-10, which has demonstrated the ability to induce both tumor rejection and foster long-lasting tumor immunity." (PMID 39204319, 2024). "M2d macrophages promote tumor progression via two primary mechanisms: firstly, by producing IL-10 and TGF-β, which induce the proliferation and migration of cancer cells, and secondly, by contributing to angiogenesis and the degradation of the extracellular matrix, which facilitate metastasis." (PMID 39796695, 2024). "IL-10 has a dual function, capable of both promoting and inhibiting tumor growth." (PMID 39840050, 2024). "This resulted in the activation of IL-10-producing Tregs and, consequently, tumor progression." (PMID 38927922, 2024). "TAM-secreted IL-10 inhibits antigen-presenting DCs, thereby hindering tumor immunity." (PMID 38715072, 2024). "The other group comprises macrophage subgroups, including Mφ-STMN1, Mφ-ISG15, tissue-resident macrophages (RTM-LMNA, RTM-MARCO), tumor-associated macrophages (TAM-MMP12, TAM-SPP1, TAM-CXCL10, TAM-HLA-DQA1), and myeloid-derived suppressor cell-like cells (MDSClike-IL10)." (PMID 39308672, 2024). "Interestingly, IL-10 neutralization also rescued both proliferation and cytotoxicity of tumor-specific CAR T cells." (PMID 39281678, 2024). "Simultaneously, it can also act on myeloid-derived suppressor cells (MDSCs) and promote the secretion of immunosuppressive cytokines such as IL-10 and IL-4, inducing the polarization of Th2 cells, inhibiting anti-tumor immunity, and promoting the occurrence and development of tumors." (PMID 39720595, 2024). "An earlier study suggested that the sustained treatment with IL-10 could induce the activation and expansion of tumor-resident CD8 + T cells in mouse tumor models." (PMID 38520006, 2024). "While IL-10 plays a pivotal role in tumor advancement, existing studies do not provide adequate evidence to substantiate an association between IL-10 concentrations in the peripheral blood of NPC patients and the intratumoral expression of IL-10." (PMID 39483474, 2024). "On the other hand, activation of STING supports tumor development by facilitating the infiltration of Tregs into the tumor microenvironment, upregulation of immune checkpoint molecules, and secretion of IL-10, which collectively serve to suppress T cell activity." (PMID 38512518, 2024). "Tumor cells can attempt to avoid the immune system by increasing the secretion of certain immunosuppressive cytokines (such as interleukin-10 and tumor growth factor-beta), upregulation of programmed death ligand 1 (PD-L1), and downregulation of MHC class I molecules." (PMID 39591094, 2024).
tumor (continued). "These increased IL-10 levels could potentially support tumor progression by suppressing effective immune responses against cancer cells." (PMID 39496002, 2024). "IL-10 is a multifunctional immunomodulatory cytokine secreted from immune cells including T lymphocytes and natural killer cells, macrophages, which can also induce tumor cell progression and metastasis via immunosuppression." (PMID 37991414, 2024). "Tumor-infiltrating lymphocytes (TILs) can often be dysfunctional and exhausted because of the factors released by the glioma and microenvironmental cells, which include TGF-β, IL-10, and CCL2, causing the recruitment of Tregs (regulatory T cells), MDSCs, and TAMs to the tumor site." (PMID 39409094, 2024). "In contrast, interleukins like IL-4, IL-5, IL-10, and IL-13, which contribute to the chronic inflammatory protumorigenic response, promote tumor progression and immune evasion through their interactions with the tumor microenvironment." (PMID 39456897, 2024). "Therefore, IL-10 is an immunoregulatory cytokine that exhibits multifunctional effects on tumor cells." (PMID 38339076, 2024). "The enrichment of Th2 cells in HCC may be mediated by STAT5A signaling, facilitating tumor growth or metastasis through immunosuppressive cytokines like IL-4 and IL-10." (PMID 38840234, 2024). "This transformation, often called immune “re-education”, renders immune cells like tumor-associated macrophages (TAMs) and resident microglia complicit in the tumor’s defense, turning them into allies that secrete immunosuppressive cytokines such as IL-10 and TGF-β." (PMID 39769374, 2024). "Enrichment in MTORC1, MYC, and UPR in the GSEA results in the high SIGLEC9 expression tumor group may promote proliferation and adaptive survival mechanisms, creating an environment conducive to cytokine production, such as IL-10, SDF-1α, and IL-2." (PMID 39727942, 2024). "It was also lower than the production of IL-10 by the tumor cells alone." (PMID 39057050, 2024). "Therefore, anti-inflammatory factors, including IL-10, become important targets for tumor prevention and treatment." (PMID 39591319, 2024). "This dichotomy stems from IL-10's diverse roles in different tumor environments 65,66." (PMID 39132165, 2024). "Furthermore, it has been shown that the EBV protein EBNA-1 activates the bone morphogenic protein (BMP) that, in turn, enhances tumor proliferation via IL-10-dependent M2 polarization of TAMs within renal cell carcinoma cell lines and patient samples." (PMID 39459945, 2024). "However, in the context of cancer, Tregs suppress anti-tumor immunity by inhibiting the activity of effector T cells and secreting immunosuppressive cytokines like IL-10 and TGF-β." (PMID 39712021, 2024). "-Induction of TNF-α and IL-12p70 levels (in vitro).-Increased body weights of mice (decreased when NPs administered with adriamycin).-Increased serum TNF-α levels and CD4+/CD8+ lymphocyte ratios and decreased serum IL-10 levels (in vivo).-Increased tumor inhibition rate and decreased tumor growth." (PMID 39591094, 2024). "Other cytokines, regardless of their proinflammatory (TNFα) or anti-inflammatory effects (IL-4, IL-10), may have diverse effects on promoting tumor growth." (PMID 39000195, 2024). "As expected, inflammatory response, tumor inflammation signature score, and IL-10 anti-inflammatory signaling pathway were positively correlated with HCP5 and LGALS3 in HCC, implying that the high level of HCP5 or LGALS3 expression is characterized by a high immune cell infiltration." (PMID 38643145, 2024). "However, tumor cells in the TME can secrete inhibitory cytokines (IL-10, TGF, and RANKL) and decrease expression of costimulatory molecules to impede the maturation of DCs, converting it to a tolerance phenotype." (PMID 38685033, 2024).
tumor (continued). "However, a significantly higher percentage of interferon-gamma (IFN-γ) producing and a lower percentage of interleukin-10 (IL-10) producing CD4+ T cells derived from the spleen of tumor-bearing A. vulgaris extract treated mice were found." (PMID 38920557, 2024). "Finally, M2d macrophages, which are induced synergistically by Toll-like receptor (TLR) agonists and adenosine receptor agonists, secrete IL-10 and VEGF, thereby promoting angiogenesis and exhibiting a strong association with tumor growth." (PMID 38779660, 2024). "Moreover, Tregs can not only interact directly with T cells and NK cells, but also indirectly inhibit the anti-tumor activity of T cells and NK cells through producing immunomodulatory cytokines such as IL-10 and TGF-β." (PMID 39735340, 2024). "Tumour-associated macrophages (TAMs), from circulating monocytes, promote tumour growth and immunosuppression in NSCLC through the release of immunosuppressive factors like IL-10 and TGF-β." (PMID 38610929, 2024). "Thus, our data indicate that the secretion of IL-10 was predictive of tumor burden after six cycles of therapy." (PMID 38473247, 2024). "Additionally, Iversen and Sioud reported the ex vivo delivery of anti-IL-10 siRNA and tumor antigens to immature dendritic cells (DCs) by means of DOTAP-based cationic liposomes to enable the DCs maturation and inhibit IL-10 expression." (PMID 37587290, 2024). "For example, CAFs could suppress the activity of immune cells by secreting immune-suppressive factors, such as Transforming Growth Factor-beta and Interleukin-10, thereby promoting the immune evasion of the tumor." (PMID 39896800, 2024). "Tumour cells are capable of escaping the immune system reaction with the help of tumour-infiltrating regulatory T-cells (Tregs) by releasing immunosuppressive cytokines, namely IL-10 and TGFβ1." (PMID 38200509, 2024). "Tumor cells may use molecules released during necroptosis, such as transforming growth factor-β (TGF-β), interleukin-10 (IL-10), etc., to establish an immunosuppressive microenvironment, which helps tumor cells escape immune surveillance." (PMID 39409087, 2024). "Notably, the crucial roles of IFN-γ, IL-1, and IL-10 have been recognized in relation to tumor immunity." (PMID 38806619, 2024). "IL-10 is a potent suppressor of anti-tumor immunity that inhibits tumor antigen presentation." (PMID 39235457, 2024). "TLR7 downregulation by AdjFluVx may contribute to the maintenance of regulatory B cell populations and IL-10 production within the tumor, encouraging tumor growth." (PMID 38476365, 2024). "The chronic inflammatory response induced by tumour cells further enhances the infiltration of neutrophils, further promoting tumour progression through the secretion of interleukin-2 (IL-2), IL-6, IL-10, tumour necrosis factor-alpha (TNF-α), and vascular endothelial growth factor (VEGF)." (PMID 38496751, 2024). "However, as multifaceted effectors, B cells can also develop an immunosuppressive phenotype characterized by the secretion of IL-10, leading to tumor progression." (PMID 38430394, 2024). "Moreover, pro-inflammation cytokines, such as Il1b, Il12b and Il18, were upregulated in the tumor of Il21r−/− mice; whereas anti-inflammation cytokines, including Il10 and Il22 were decreased in the tumor of Il21r−/− mice." (PMID 38720319, 2024). "Increased IL-10 expression has been demonstrated to suppress anti-tumor immunity." (PMID 39456552, 2024). "Thus, circLOC729852 functions as an oncogene in BLCA by inducing secretion of IL‐10 by the M2 TAMs, which then facilitates tumour cell growth and migration." (PMID 38506082, 2024). "A more recent study showed that the expression of IL-10 in tumor-infiltrating regulatory T cells may result in the exhaustion of intratumoral CD8 + T cells." (PMID 38520006, 2024). "The discrepancies may be attributed to the tumor types or different stages of T cells that respond to IL-10." (PMID 38520006, 2024).
tumor (continued). "These drugs, in combination with therapies aimed at neutralizing the T cell suppressive activities of IL-6, IL-9 and/or IL-10, may reasonably help reducing immune evasion of tumor cells, thereby ameliorating the clinical management of the disease." (PMID 39281678, 2024). "However, a recent study has shown that B cells synthesize and secrete the neurotransmitter GABA, which induces IL-10 secretion from macrophages and suppresses anti-tumor T-cell responses." (PMID 38911374, 2024). "Additionally, inhibiting IL-10 expression or function can also reduce tumor invasiveness and metastasis, thereby improving patient prognosis." (PMID 38562480, 2024). "The prognostic impact of high IL-10 levels appears to be consistent across tumor type." (PMID 39199610, 2024). "Additionally, these elements induce the differentiation of MHC class II+ macrophages, enhancing L‐Arginase activity and IL‐10 secretion at the tumor site, thereby promoting cancer progression." (PMID 39070181, 2024). "Our findings suggest that physical activity may modulate IL-10 signaling, thereby promoting a more effective anti-tumor immune response." (PMID 39769247, 2024). "The dysregulation, indicated by an elevated IL-10/IL-6 ratio, may create a less conducive tumor microenvironment for PD-1 antibody therapy." (PMID 39227388, 2024). "While IL-10 is an anti-inflammatory cytokine released by macrophages, eosinophils, mast cells, dendritic cells, NK cells, and cancer cells, acts as an immunosuppressive factor and has pro-tumour and anti-cancer activity." (PMID 39619199, 2024). "These cells significantly contribute to immune regulation while also promoting infection and tumor progression; Activation of M2c macrophages by either IL-10 or glucocorticoids results in the release of numerous anti-inflammatory cytokines (IL-10, TGF-β, IL-1RA)." (PMID 38736879, 2024). "However, they can also exert a pro-tumor function by secreting IL-10, which inhibits CD4+ and CD8+ T cells." (PMID 38913547, 2024). "Meanwhile, the immunosuppressive effects of IL-4 and IL-10 secreted by Th2 cells could further regulate tumor growth and metastasis." (PMID 37181805, 2023). "However, from the perspective of immunosuppression, immunosuppressive factors such as IL-6, TGF-β, and IL-10 produced from tumor cells attenuate the activation level of DCs." (PMID 37553633, 2023). "Besides, in vitro and in vivo preclinical studies demonstrated that incomplete RFA significantly upregulated IL-10 expression, leading to an inhibited immune response in the residual tumor." (PMID 36831664, 2023). "IL‐10, as an immunosuppressive cytokine, can be produced by monocytes or even tumor cells." (PMID 35864742, 2023). "This study showed malignant cells in developing tumors expressed anti-inflammatory cytokine IL-10 and its expression increased as the tumor progressed to late stages, suggesting that NK cells in the tumor and its vicinity are persistently exposed to tumor-induced IL-10." (PMID 36830840, 2023). "Notably, IL-10 expression levels were significantly higher in the tumor tissues and serum samples of patients with cancer." (PMID 38102207, 2023). "Additionally, in transgenic mice models, IL-10 produced by TAMs is the key mediator in tumor resistance to paclitaxel and carboplatin." (PMID 36825088, 2023). "RNA analysis by qPCR with Treg cell marker genes revealed that SRC-3 KO Tregs in spleens of tumor-bearing SRC-3d/d:Treg female mice had elevated expression of anti-inflammatory cytokines such as Tgf-β, Il-10, and Il-35 compared to Tregs from the spleens of tumor-bearing SRC-3f/f female mice." (PMID 37253006, 2023). "In addition, it has been shown that M2 TAM inhibits anti-tumor immunity by downregulating M1 through the secretion of anti-inflammatory cytokines, including IL-10." (PMID 37024932, 2023). "CD73 positive NK cells can secrete TGFβ and IL-10, and thereby act as tumor promoters." (PMID 37691935, 2023).